KRAS (KRas proto-oncogene, GTPase)
Diseases named in the same sentence as KRAS in open-access papers (continued):
Sharing a sentence is not in itself a finding about the gene and the disease.
cancer (continued). "Evidences of the close link between mutant KRAS, the pyruvate dehydrogenase complex (PDHC) and the Warburg Effect in cancer are rapidly increasing." (PMID 33664850, 2021). "BI-3406, a novel SOS1-KRAS interaction inhibitor designed to target the catalytic domain of SOS1, has been combined with trametinib and sensitized KRAS-driven cancers to MEK inhibition in mouse models." (PMID 34946644, 2021). "We therefore sought to better molecularly characterize the mechanisms of resistance to single and combined MEKi and ERKi in oncogenic KRAS-, HRAS- or BRAF-driven cancer cells by focusing analyses on potential rewiring of intracellular signaling cascades." (PMID 33924486, 2021). "Mutations on the G12/G13 positions in Ras proteins, including HRAS, KRAS, and NRAS, showed increased sensitivity to MEK inhibitors AZD6244 and PD-0325901 in multiple cancer types (BLCA, CESC, HNSC, PAAD, THYM, UCEC, and UCS)." (PMID 33741950, 2021). "Encouraged by these findings, we have expanded the assessment to various cancer cells harboring KRAS G12D (AsPC-1), KRAS-G12V (SW480, DU-145), KRAS-G12C (H358), KRAS-G13D (MDA-MB-231), KRAS-Q61L (HT-29), and NRAS-Q61L (OCI-AML3)." (PMID 34956887, 2021). "It was shown that high levels of AGO2 protein enhanced neoplastic transformation driven by KRAS mutants, whereas knockout of AGO2 resulted in the growth arrest of KRAS-dependent cancer cells." (PMID 33668654, 2021). "Several studies in mouse models have demonstrated the importance of MYC in KRAS-driven oncogenesis and genetic suppression of MYC impairing the growth of KRAS-driven cancer cells." (PMID 34944853, 2021). "KRAS and HRAS are two well-known oncoproteins that upregulate autophagy as a pro-survival mechanism for cancer cells to overcome the metabolic stress." (PMID 33802014, 2021). "Covalent quinazoline-based switch II compounds effectively inhibit GTP loading of KRAS G12V, MAPK phosphorylation, and the growth of cancer cells driven by KRAS G12C." (PMID 34830757, 2021). "Furthermore, only 10 patients showed a regressive trajectory of KRAS (mutKRAS → wtKRAS) and this was related to the lower incidence of this effect if compared to the progressive trajectory (wtKRAS → mutKRAS) which represents an advantageous gain for cancer cells." (PMID 33854968, 2021). "For instance, dysregulation of phosphorylation pathways is often a trigger of pathologies, such as human cancers, and many typical oncogenes, such as HER2 and KRAS, directly or indirectly activate downstream phosphorylation cascades." (PMID 34680108, 2021). "Although the role of BRAF, KRAS, and KIT in transcriptomic alterations, tumorigenesis, and progression of several cancers has been partially elucidated, bioinformatics analysis in SKMs has yet to be confirmed." (PMID 34769348, 2021). "These VHL–monobody fusions selectively and efficiently degraded KRAS(G12C) in RASless MEFs, as well as endogenous RAS in PATU8902 and H23 cancer cell lines." (PMID 33976200, 2021). "Highly significant expression changes in 17 known cancer genes such as ERBB2, KRAS and SMAD4 were observed by analyzing the RNA sequencing data of 116 EACs, showing a correlation with a high degree of chromosomal instability." (PMID 34503107, 2021). "Interestingly, HPV-driven cancers had a distinct mutational profile with prominent APOBEC signatures, while HPV negative cancers were predominantly endometrial-like cervical cancers with a mutational profile resembling endometrial cancer (ARID1A, PTEN, and KRAS mutations)." (PMID 34283069, 2021).
cancer (continued). "tested targeting the mutant KRAS, using CRISPR-Cas9 in various cancer cell lines (SW403, SW480, SW680, HT29, LS513, LoVo) and analyzed its effect on cell proliferation, survival and cancer growth in vitro and in vivo." (PMID 34781949, 2021). "Many well‐known proteins that play crucial roles in cancer like IDH1, PTEN, and KRAS were included in this network." (PMID 34247449, 2021). "In summary, we describe the discovery of CCT3833, a new panRAF/SRC inhibitor, and show that it is effective in KRAS-mutant cancer models, because RAF and SRC are central nodes in KRAS-mutant cancers." (PMID 33130216, 2021). "Examination of KRAS and BRAF mutation statuses is indicated in metastatic cases since wildtype KRAS and BRAF carcinomas are eligible for anti-EGFR therapy." (PMID 33671994, 2021). "First, it was recently shown that oncogenic KRAS-induced NRF2 upregulates glutaminolysis, which promotes chemoresistance in PDAC; however, we were unable to explore the role of NRF2 in cancer metabolism in the present study." (PMID 32629871, 2020). "Despite the fact that KRAS protein mutations are frequently observed in cancers with the glycine 12 mutation, the computational analyses from the Catalogue of Somatic Mutations in cancer revealed nonrandom frequencies of changes of other amino acids as well at this position." (PMID 33113880, 2020). "In order to translate our findings to a more physiologically relevant cancer model, we repeated our cetuximab and EGF experiments in KRAS wild-type patient-derived CRC organoids, ORG12620." (PMID 32481658, 2020). "Evidence from this study supports the critical role of ICMT in the negative regulation of both KRAS and TAZ function in supporting cancer cell self-renewal." (PMID 32561852, 2020). "In KRas mutant cancer cells, SAH‐SOS1A impaired cell viability in a manner dependent on KRas inhibition." (PMID 30869179, 2020). "Therefore, the knockdown of KRAS showed stronger effect of ALDH1L1 expression compared to over expression of KRAS in cancer cells, because all transcription factors, as well as downstream signaling molecules, may be required to increase the transcription activity of ALDH1L1." (PMID 32481524, 2020). "By comparing the genomic alteration of 20q13.33 gain with APC and KRAS mutations (62.63% vs 42.93 and 23.73%, respectively), which are currently identified as the most important targets for CRC therapy, the results support that 20q13.33 gain may have been involved in the development of cancer." (PMID 33087131, 2020). "KRas in turn promotes EIF5A protein expression, thus generating a positive feed forward loop that promotes glutamine-dependent cancer cell growth." (PMID 33303756, 2020). "Previous studies have paid great attentions to cancer-related genes, e.g. hTERT, c-MYC, BLC2, KRAS, and VEGF, which contain enriched G4 motifs in their promoter regions." (PMID 32257105, 2020). "By posttranslational carboxylmethylation, ICMT modulates KRAS function in engaging RAF–MEK signaling, which in turn affects TAZ stability and cancer stem cell self-renewal." (PMID 32561852, 2020). "Major drivers of these cancers include BRAF (V600E, V599E) and/or KRAS (G12C, G12D) along the MAPK pathways while immunotherapies were considered as a monotherapy or in combination in those tumors expressing PD-1 ligands." (PMID 32260561, 2020).
cancer (continued). "Our objective is to design and evaluate hybridization properties of multiple model helices containing three cancer-related probes, BRAF, KRAS, and EGFR, bound to complementary and mismatched RNA." (PMID 36703315, 2020). "We reviewed recent evidence on the signaling interplay between the NF-κB and oncogenic KRAS signaling pathways in PDAC cells and their collective contribution to cancer inflammation." (PMID 32961746, 2020). "Mechanistically, DCLK1 regulates NOTCH, NF-kB, KRAS, and WNT molecular signaling pathways that promote cancer growth and progression as well as support EMT and stemness of cancer cells." (PMID 31979136, 2020). "In KRAS oncogenic mutant cancer cells, KLF11 inhibits BrdU incorporation, increases apoptosis, and inhibits the KRAS-mediated foci and agar colony formation." (PMID 32331236, 2020). "KRAS plays an important role in both the PI3K-Akt and MAPK signaling pathways and has been reported to promote chemoresistance in human cancers." (PMID 33072545, 2020). "A great amount of GLUT1 in KRAS and BRAF mutant cells can be a target for high doses of vitamin C, which can ultimately lead to ROS generation and cancer cell death." (PMID 33352824, 2020). "These compounds resulted in strongly reduced proliferation in oncogenic KRAS-dependent Panc-Tu-I and MIA PaCa-2 cells but less activity on KRAS-independent cancer cell lines (PANC-1 and BxPC-3)." (PMID 32770300, 2020). "Yun's article stating that Vc selectively kills KRAS and BRAF mutant CRC makes us regain confidence in the study of Vc, a controversial cancer suppressor." (PMID 33293956, 2020). "Consistently, treatment with G4 stabilizing ligands, a cationic phthalocyanine tetrakis-(diisopropyl-guanidine) phthalocyanine (Zn-DIGP), and TMPyP4, targeting the promoters of KRAS and HRAS, decreased RAS expression in cancer cells." (PMID 33198362, 2020). "However, there are no effective methods to treat KRAS‐mutated cancers." (PMID 31709772, 2020). "More importantly, the hsa05200 pathway derived from both ME and CNV signatures, which includes EGFR, KRAS, MDM2, STAT1 and other signature genes identified by us, is shown to be closely related to initiation and progression of cancer." (PMID 32030321, 2020). "The comparison between CA-KRAS(C186S) and CA-KRAS supports the notion that the C-terminal modification is important for the function of KRAS in the regulation of TAZ and cancer cell stemness." (PMID 32561852, 2020). "KRAS (Kristen Rat sarcoma), one of the RAS isoforms, plays an important role in human cancers acting upstream of BRAF." (PMID 32637031, 2020). "YAP1 has also been shown to be required for KRAS and ST-mediated transformation, providing further evidence that YAP1 is critical for cancer development and maintenance." (PMID 31913126, 2020). "In this study, we provide compelling evidence that supports a previously unidentified role of ICMT in the regulation of TAZ degradation via modulating the function of mutant KRAS and its downstream RAF–MEK signaling to support cancer cell self-renewal." (PMID 32561852, 2020).
cancer (continued). "For example, oncogene products of KRAS and dystrophin (DMD) proteins demonstrated reduced expressions in several cancer types, in spite of the up-regulated status of these oncogenes." (PMID 33287876, 2020). "We performed a comparison of the KRAS-specificity of the KRAS degrader with the pan-RAS degrader in a stably transduced H358 (lung, KRASG12C) cancer cell line." (PMID 32591521, 2020). "It has been reported that the rates of KRAS mutations in normal ovaries, benign mucinous ovarian tumors, mucinous ovarian borderline tumors, and MOC are 0%, 57%, 90%, and 76%, respectively, suggesting that it may play a major role in the progression from benign tumors to carcinomas." (PMID 32556513, 2020). "In contrast, genes that replicate later and are downregulated are enriched in terms related to cancer such as EMT, TNFα signalling, KRAS signalling, cell movement and cell proliferation." (PMID 30679435, 2019). "ERBB family proteins have proven to be far more amenable to pharmacological inhibition than KRAS itself, and multiple ERBB inhibitors are approved for the treatment of cancers expressing mutant or amplified ERBB isoforms." (PMID 31032816, 2019). "The proximal interactions of these SNAREs were assessed by a similar experimental design for KRAS, HRAS, and NRAS in cells derived from the most cancer-relevant tissues for each isoform." (PMID 31712554, 2019). "Serving as an activator of the MAPK, PI3K, and KRAS pathways, EGFR contributes to proliferation and metastasis of cancer cells and can be activated upon UV exposure." (PMID 30683916, 2019). "The major molecular alterations driving cancer of the colonic epithelium involve dysfunction of the WNT/APC and KRAS/MAPK pathways, DNA repair and methylation, and chromosomal instability." (PMID 30925167, 2019). "LIN28 inhibits Let-7 miRNA maturation to promote the expression of Let-7 targets HMGA2, KRAS, MYC22, and HRAS in cancer cells." (PMID 31712708, 2019). "Gene-set enrichment analysis of hallmarks of cancer pathways has shown that several important pathways are upregulated in response to SK1/SK2 KD, most notably KRAS, IL2/STAT5, EMT and TNF/NFκB (SK1 KD) and EMT, G2/M and E2F (SK2 KD)." (PMID 30971929, 2019). "Collectively, our discovery of a druggable ADAM17‐sIL‐6R axis in KRAS mutant LAC represents an attractive new strategy for the development of therapies for LAC and potentially other oncogenic KRAS‐addicted cancers." (PMID 30833304, 2019). "For example, oncogenes including MYC, KRAS, and CCND1 showed strong CES with increasing copy numbers, corroborating the recent studies about cancer dependency on these gene amplifications." (PMID 31732481, 2019). "Under conditions of low nutrients, mutant KRAS, a main oncogene of PDAC, is able to drive macropinocytosis as a source of amino acids from extracellular proteins for the cancer cells." (PMID 31058816, 2019). "As such, the effect of monoclonal antibodies against these kinases often depends on the KRAS or BRAF status of the tumor, which is another reason why understanding the molecular pathogenesis of the cancer is crucial in deciding the appropriate treatment." (PMID 31366129, 2019). "Despite the apparent homology and similar structural organization between KRAS and NRAS, numerous studies point to isoform-specific functions and differences in tissues and cancer hallmarks affected." (PMID 31816869, 2019).
cancer (continued). "The inhibition of PP2A in KRAS-mutant LC cells was shown to mediate MEK inhibitor resistance, highlighting the importance of functional PP2A in LC as a key modulator in cancer treatment." (PMID 31623614, 2019). "As our multiple in vivo studies suggested, targeting of KRAS by miR-873 is expected to be a highly efficient therapeutic strategy in PDAC, TNBC, and other KRAS-driven cancers." (PMID 30654191, 2019). "In the combined assay of mutant KRAS ctDNA and CA19-9, the sensitivity for PC diagnosis was obviously improved especially in the early cancer stages." (PMID 31850201, 2019). "We identified 156 focal amplifications and 69 focal deletions, in well-known oncogenes, such as ERBB2, CCNE1, KRAS, MYC, EGFR, and CDK6, and cancer-related genes such as GATA4, GATA6, CD44 and ZNF217." (PMID 31570735, 2019). "In this review, we will introduce cellular plasticity and its effect on cancer progression and therapy resistance and then summarize the drivers of EMT with an emphasis on KRAS effector signaling." (PMID 31681587, 2019). "Small molecule inhibitors and monoclonal antibodies against various member of this family have proven efficacy in different cancer settings, such as EGFR inhibitors in KRAS-wild type lung cancer and HER2 antibodies in HER2 positive breast cancer." (PMID 30841549, 2019). "Moreover, in both in vitro and in vivo models, KRAS G12C decreased the levels of glutamine and glutamate, two amino acids involved in nitrogen balance maintenance, supporting the central role of glutaminolysis and nitrogen anabolism to provide energy for cancer cell growth and proliferation." (PMID 31681616, 2019). "Because miR-21 overexpression and KRAS mutation have been extensively reported to be a part of a PDAC signature with a strong clinical correlation for PDAC progression and survival, we hypothesized that dual targeting of these two key players could improve the anti-cancer effects." (PMID 31523393, 2019). "Therefore, given the lack of effective therapeutic strategies against KRAS-mutated cancers, it might be of interest to test the capacity of afatinib alone or combined with other drugs to inhibit the growth of EGFR/KRAS co-mutated NSCLC in human patients." (PMID 31266248, 2019). "KRAS4B, the major KRAS isoform studied in cancer, contains a C-terminal poly-basic region that mimics lipidation." (PMID 31712554, 2019). "Both HRAS and KRAS (KRAS4A and KRAS4B) are members of the small GTPase RAS subfamily that is highly sensitive to GTP activation in cancer cells." (PMID 31600993, 2019). "Oncogenic mutant RAS proteins (KRAS, NRAS and HRAS) are prevalent in up to 30% of all human cancers." (PMID 31484165, 2019). "The cancer-upregulated exRNAs that were also most frequently detected among the cancer samples that came from RAC2, KRAS, and CAMK2A." (PMID 31481608, 2019). "In this review, we will introduce cellular plasticity and its effect on cancer progression and therapy resistance and then summarize drivers of EMT with an emphasis on KRAS signaling." (PMID 31681587, 2019). "Other genes which feature across multiple types of cancer and enter the top five driver-gene list are PIK3CA (in 6), KRAS (in 5) and CTC-297N7.11 (in 4)." (PMID 31530827, 2019). "Using gene ontology (GO) enrichment analysis, we identified that angiogenesis, cell cycle progression, epithelial-mesenchymal transition (EMT), KRAS, and c-Myc signaling pathways were significantly downregulated in the USP22−/− cancer cells." (PMID 31842906, 2019). "Peaks involving important cancer genes such as CCND1, EGFR, ERBB2, FGFR1, AKT1, MYC, KRAS and CDKN2A/2B, which were confirmed in our data." (PMID 30131072, 2018). "Similar results were obtained in all the KRAS-mut lung (A427) and pancreatic (PACA44, HPAFII, L3.6pl and PANC1) cancer cell lines analyzed." (PMID 29986755, 2018).